IGLC2 (immunoglobulin lambda constant 2)
Description:
Constant region of immunoglobulin light chains. Immunoglobulins, also known as antibodies, are membrane-bound or secreted glycoproteins produced by B lymphocytes. In the recognition phase of humoral immunity, the membrane-bound immunoglobulins serve as receptors which, upon binding of a specific antigen, trigger the clonal expansion and differentiation of B lymphocytes into immunoglobulins-secreting plasma cells. Secreted immunoglobulins mediate the effector phase of humoral immunity, which results in the elimination of bound antigens. The antigen binding site is formed by the variable domain of one heavy chain, together with that of its associated light chain. Thus, each immunoglobulin has two antigen binding sites with remarkable affinity for a particular antigen. The variable domains are assembled by a process called V-(D)-J rearrangement and can then be subjected to somatic hypermutations which, after exposure to antigen and selection, allow affinity maturation for a particular antigen.
Synonyms: IGLC
Tractability: Antibody: its Gene Ontology location is reachable by antibodies, with high confidence; UniProt places it where antibodies can reach, with medium confidence.
Gene: Immunoglobulin constant (C) gene on chromosome 22 (22,900,976 to 22,901,437, forward strand). Ensembl gene ENSG00000211677.
Subcellular location: Secreted; Cell membrane
Pathways (Reactome):
Immune System: Antigen activates B Cell Receptor (BCR) leading to generation of second messengers; CD22 mediated BCR regulation; Classical antibody-mediated complement activation; FCERI mediated Ca+2 mobilization; FCERI mediated MAPK activation; FCERI mediated NF-kB activation; FCGR activation; Fc epsilon receptor (FCERI) signaling; Immunoregulatory interactions between a Lymphoid and a non-Lymphoid cell; Initial triggering of complement; Regulation of Complement cascade; Regulation of actin dynamics for phagocytic cup formation; Role of LAT2/NTAL/LAB on calcium mobilization; Role of phospholipids in phagocytosis
Disease: FCGR3A-mediated IL10 synthesis; FCGR3A-mediated phagocytosis; Potential therapeutics for SARS
Hemostasis: Cell surface interactions at the vascular wall
Vesicle-mediated transport: Scavenging of heme from plasma
Gene Ontology:
Molecular function: antigen binding
Biological process: immunoglobulin mediated immune response
Cellular component: blood microparticle; extracellular exosome; extracellular region; IgG immunoglobulin complex; plasma membrane
Genetic constraint (gnomAD): Missense variants: 33 observed, 35.83 expected, observed/expected ratio (o/e) 0.92, 90% interval 0.7 to 1.23. Synonymous variants: 14 observed, 15.45 expected, observed/expected ratio (o/e) 0.91, 90% interval 0.6 to 1.41.
Homologues: Orthologues: mouse Iglc1 (72% identical), rabbit IGLL1 (70% identical), rat Iglc1 (66% identical), mouse Iglc4 (65% identical), mouse Iglc3 (63% identical), mouse Iglc2 (61% identical). Paralogues in human: IGLC3 (99% identical), IGLC1 (96% identical), IGLL5 (95% identical), IGLC7 (93% identical), IGLL1 (84% identical), IGKC (37% identical), IGHA2 (36% identical), IGHA1 (34% identical), IGHM (33% identical), IGHG1 (31% identical), IGHG2 (31% identical), IGHG3 (31% identical), and 65 more.
Diseases named in the same sentence as IGLC2 in open-access papers:
IGLC2 is named in the same sentence as 19 diseases in open-access papers, as found by Europe PMC text mining. Sharing a sentence is not in itself a finding about the gene and the disease. The quoted sentences say what the papers report.
COVID-19 (4 papers, 2022 to 2024). A disease caused by infection with severe acute respiratory syndrome coronavirus 2. "In particular, four of the shared six genes between the McClain and Lee data were immunoglobulin encoding genes: IGHG1, IGHG3, IGHG4, and IGLC2, all of which were consistently upregulated in a COVID-19 specific manner across the datasets." (PMID 35991542, 2022). "One of the most observed COVID-19-specific signatures at the transcriptional level concerns immunoglobulin-related genes, including IGLC2, which were found to be consistently upregulated in correlation to COVID-19 disease across different datasets." (PMID 36834989, 2023). "COVID-19 and IAV coexpressed genes might be associated with essential biological functions of B cells; for example, IGHG3 and IGLC2 were B cell marker genes." (PMID 37956172, 2023). "Moreover, IGLC2 has been highlighted as upregulated in the form of transcript in B-cells of SARS-CoV-2 patients, and as a protein in sera of COVID-19 patients, where its level has not been normalised after patient recovery." (PMID 36834989, 2023).
breast carcinoma (2 papers, 2022 to 2023). "All these features make IGLC2 have the potential to be a biomarker to predict prognosis, even for identifying breast cancer patients who can benefit the most from immune checkpoint blockade treatment." (PMID 36338982, 2022). "Meanwhile, IGLC2 and PRDX4 were downregulated 73-fold and sevenfold, respectively, and their high expression is associated with better disease-specific or relapse-free survival in breast cancer." (PMID 37391754, 2023).
diabetes (2 papers, 2024 to 2025). "The most significant increase in protein levels was observed for immunoglobulin lambda constant 2 (IGLC2), which increased by 2.29-fold in the diabetes group, while methanethiol oxidase (SELENBP1) showed the most significant decrease in the diabetes group." (PMID 40142159, 2025).
cardiomyopathy (1 paper, 2021). A disease of the heart muscle or myocardium proper. "Cardiomyopathy is a common adverse effect of chemotherapeutic agents (i.e., trastuzumab and doxorubicin) for BC, which may partially explain why IGLC2 is related to HCM, DCM, and ARVC." (PMID 35155184, 2021). "IGLC2 may serve as a potential biomarker to monitor or reduce cardiomyopathy in BC chemotherapy." (PMID 35155184, 2021).
lung carcinoma (1 paper, 2022). "Notably, elevated expression levels of production of immunoglobulin-related genes IGHG4, IGKC, IGLC2, IGHG3, and PLAU were detected in the SPP1-Mφ cluster, suggesting the proinflammatory and anti-tumor functions of this cluster in lung cancer." (PMID 36008393, 2022).
malignant brain tumor (1 paper, 2015). "Using Mass Spectrometry (MS), we initially found that 22 proteins were differentially expressed and then validated deleted in malignant brain tumor-1 (DMBT1) and Ig lambda-2 chain C region (IGLC2) using Western Blotting." (PMID 25873979, 2015).
multiple myeloma (1 paper, 2015). "IGLC2 is encoded by chromosome 22 and is increased in several pathological conditions including HIV infection, multiple myeloma, and influenza A virus infection, suggesting that this induction could be involved in protection against infection and immune response." (PMID 25873979, 2015).
tumor (18 papers, 2006 to 2025). "Therefore, we speculated that IGLC2 is a biomarker of the humoral immune system and associated with tumor-infiltrating lymphocytes (TILs)." (PMID 35155184, 2021). "The results showed that tumor cells in metastatic LN expressed high levels of IGLC2, IGHG4, and IGKC, and GO analysis showed various immune-related signaling pathways." (PMID 36569924, 2022). "The results showed that CAFs in P-LNs were associated with the high expression of NFIB, IGLC2, IGHG4, C7, and CCL19, while CAFs in tumor 3 had high expression of DIO2, LGALS1, WNT5A, NEAT1, and MMP11 in the tumor." (PMID 36569924, 2022). "We next compared the expression profiles of tumor‐derived and normal tissue‐derived B‐cell subsets IgA+IGLC2+ plasma and cycling B cells." (PMID 33463049, 2021). "For IgA+IGLC2+ plasma cells, allograft rejection, interferon‐alpha response, interferon‐gamma response, and inflammatory response were enhanced in the tumor‐derived cells, indicating the involvement in promoting inflammatory responses in tumors." (PMID 33463049, 2021). "►The high expression of IGLC2 is related to favorable relapse-free survival, distant metastasis-free survival, tumor size, and TNBC molecular subtypes." (PMID 35155184, 2021). "We confirmed that MDA-MB-231 tumor cells expressed IGLC2, subverting the traditional finding of generation by immune cells." (PMID 35155184, 2021). "In this study, IGLC2 was also expressed in tumor cells and played important roles in the prognosis of TNBC." (PMID 35155184, 2021). "A low IGLC2 mRNA expression was exhibited in large tumor-size tissues; especially in tumors of any size with direct extension." (PMID 35155184, 2021). "MTT assay was used to ascertain the role of IGLC2 in tumor proliferation." (PMID 35155184, 2021). "We speculated that IGLC2 is a biomarker of immune cell infiltration and anti-tumor immune activities." (PMID 35155184, 2021). "We analyzed the role of IGLC2 in tumor migration using the transwell cell migration assay." (PMID 35155184, 2021). "The lower expression of IGLC2 was associated with unfavorable tumor size and metastasis although there was no statistical significance." (PMID 35155184, 2021). "In the epithelial pairwise comparison, we observed a significant upregulation of IGLC2 and IGKC, suggesting an active immune response initiated at the root epithelial cell population, where tumor proliferation appears to trigger EMT programming." (PMID 40950184, 2025). "In RNAss database, tumor stemness was confirmed to be negatively correlated with the expressions of IGLC1 (r = -0.15, P = 0.01), IGLC2 (r = -0.16, P = 0.01), IGLC3 (r = -0.15, P = 0.01), and IGLC6 (r = -0.13, P = 0.03) respectively." (PMID 37784026, 2023). "Tumor stemness was negatively correlated with the expressions of 4 IGLCs (IGLC1, IGLC2, IGLC3, and IGLC7) respectively in CESC tissues." (PMID 37784026, 2023). "Except for IGLC4, IGLC5, and IGLC7, 4 IGLC (IGLC1, IGLC2, IGLC3, and IGLC6) expressions were positively correlated with infiltration scores of 6 tumor-infiltrating immune cells (B cell, T cell CD4, T cell CD8, neutrophil, macrophage, and DC)." (PMID 37784026, 2023). "In DNAss database, we found that tumor stemness was negatively correlated with the expressions of IGLC1 (r = -0.14, P = 0.02), IGLC2 (r = -0.13, P = 0.02), IGLC3 (r = -0.13, P = 0.02), and IGLC7 (r = -0.14, P = 0.01) respectively in CESC tissues." (PMID 37784026, 2023). "Cancerous squamous cell‐associated genes such KRT5, CDKN2A, and SERPINB3 were mainly enriched in the Stereo‐seq tumor areas, IGKC and IGLC2 were enriched in inflammatory areas, VIM in stromal areas, ADRA2A in blood vessels, and MUC5B in glands." (PMID 35986392, 2022). "In addition, the lesion IgG + and mucosa IgA + spots exhibited divergent B-cell receptor V/C gene usage, with IGLC2, IGLC3, IGLV3-1, and IGKV4-1 all enriched in the tumor, suggesting a difference in the adaptive response between the two plasma cell types." (PMID 38110959, 2023).
tumor (continued). "We then analyzed and marked the top 20 DEG genes in tumor core regions and found that IGHG1, IGHG3, IGHG4, IGKC, and IGLC2 (effector markers for humoral immunity) were notably downregulated in core regions, possibly indicating an immunosuppressive microenvironment (ISME)." (PMID 35673582, 2022). "Based on the relatively well-defined multifunctional characteristics including immune regulation, epithelial differentiation, and tumor suppression in a number of tumors, we chose DMBT1 and IGLC2 to analyze further Yogic breathing samples obtained from the clinical trial." (PMID 25873979, 2015).
cancer (6 papers, 2018 to 2024). A tumor composed of atypical neoplastic, often pleomorphic cells that invade other tissues. "IGLC2 shows a potentially high mutation burden in a pan-cancer context." (PMID 35155184, 2021). "CCL15 was also increased as the pseudo-time progressed and was dominant in the end stages of the pseudo-time axis; Conversely, other key molecules such as IGHG1, IGHG3, IGHG4, IGKC, IGLC2 decreased gradually among all the carcinoma sectors in HCC1 and HCC4." (PMID 35673582, 2022).
lymph node (1 paper, 2021). "Therefore, no significant prognostic value was observed with IGLC2 in lymph node-positive TNBC." (PMID 35155184, 2021). "Meanwhile, IGLC2 was not a significant prognostic predictor of RFS and DMFS for lymph node-positive TNBC." (PMID 35155184, 2021).
IGLC2 also shares sentences with these, for which no sentence is quoted: triple-negative breast carcinoma (3 papers); infection (2); atherosclerosis (1); bladder cancer (1); diabetic kidney disease (1); melanoma (1); metastatic tumors (1); non-small cell lung carcinoma (1); viral infections (1).